PPARG (peroxisome proliferator activated receptor gamma)
Diseases named in the same sentence as PPARG in open-access papers (continued):
Sharing a sentence is not in itself a finding about the gene and the disease.
tumor (continued). "To determine if PPARγ is also involved in FABP4 overexpression in tumor cells exposed to adipocyte-derived factors, we treated tumor cells with either PPARγ agonist rosiglitazone (ROSI) or with Adipo CM in the absence or presence of PPARγ antagonist GW9662." (PMID 24240026, 2013). "We show that NT5E is a target of the TNF-α signaling in vitro; the tumor suppressor PPARγ acts as a novel NT5E antagonist that positively and concomitantly regulates DCBLD2 in a cancer cell context-dependent manner." (PMID 24133572, 2013). "It is well known that PPARγ receptors are expressed in a variety of tumor cells and activation of PPARγ with ligands leads to either inhibition of cell proliferation or by induction of apoptosis." (PMID 24204697, 2013). "In vivo experiments further showed that the disruption of the negative feedback loop by the AKT inhibitor triciribine significantly facilitated the PPARγ agonist rosiglitazone-mediated inhibition of tumor growth." (PMID 24023668, 2013). "Altogether, these results suggest that epigenetic mechanisms play a crucial role in PPARG deregulation and tumor development." (PMID 22848209, 2012). "Collectively, the large wealth of data accumulated so far on the specific role that PPARG plays in tumorigenesis supports a cell growth restraining function, hence a tumor repressor activity." (PMID 22848209, 2012). "PPARγ actually displays antiangiogenic properties which have been proposed to disrupt the symbiosis between the tumor and the host cells in the tumor bed and which impact negatively several proangiogenic factors among which VEGF, and βFGF." (PMID 22654896, 2012). "For the first time we also suggest a possible explanation for the elevated expression of PPARG in this type of tumor through a focal high level amplification at 3p25.2." (PMID 23114535, 2012). "The anti-tumor effect of PPARγ activation is exerted by the induction of cell cycle arrest rather than by induction of apoptosis." (PMID 23049949, 2012). "All together, these data strongly support a role for PPARγ as tumor suppressor; in contrast, a few studies have provided evidence that it acts as a tumor promoter." (PMID 22848209, 2012). "In particular, a possible role for PPARγ as a tumor suppressor and as an inducer of differentiation of cancer stem cells has been explored, and its protein level in tumor specimens has been identified as a significant prognostic marker." (PMID 23028383, 2012). "Preclinical studies using PPARγ agonists, specifically TZDs such as rosiglitazone and pioglitazone, have been shown to inhibit tumor growth in many types of cancer." (PMID 22934105, 2012). "UHRF1 upregulation is inversely correlated with PPARG expression in an advanced tumor stages CRC subgroup." (PMID 22848209, 2012). "The peroxisome proliferator-activated receptorγ (PPARγ) is a key regulator of metabolism, proliferation, inflammation and differentiation, and upregulates tumor suppressor genes, such as PTEN, BRCA1 and PPARγ itself." (PMID 22538444, 2012). "For example, Yen and coworkers reduced PPARγ levels in tumor cells using siRNA, which abolished rexinoid-mediated inhibition of invasion." (PMID 22934105, 2012). "Work from our laboratory showed that in nude rats, orthotopic implantation of human NSCLC H2122 cells that overexpressed PPARγ inhibited tumor growth and metastasis, and prolonged survival compared to implantation of control H2122 cells." (PMID 22934105, 2012). "Our results support previous reports of PPARγ agonists describing both a direct anti-tumor and a broad spectrum of anti-stromal, anti-angiogenetic and immuno-modulating activities." (PMID 23049949, 2012). "High concentrations of PPARγ are found in tumor endothelium and in healthy skin endothelial cells, and PPARγ activation can induce PPARγ expression in tumor endothelial cells." (PMID 23213321, 2012).
tumor (continued). "This discrepancy has been ascribed to in vivo effects of “tumor interactions,” differences in PPARγ activation magnitude and PPARγ-independent effects of thiazolidinediones." (PMID 22991505, 2012). "PPARγ was moderately increased in some tumors but more frequently down-regulated, consistent with the putative tumor suppressor role attributed to this NHR." (PMID 23049921, 2012). "Genetic mouse models using targeted knockouts of PPARγ in either cancer cells or cells in the tumor microenvironment will also be informative." (PMID 22934105, 2012). "Although PPARγ function in colon carcinogenesis has been controversial for long time, more recent evidence supports a role as tumor suppressor." (PMID 22991505, 2012). "In a mouse mammary tumor model, treatment with the PPARβ/δ agonist GW501516 accelerated tumor formation, while a PPARγ agonist GW7845 delayed tumor growth." (PMID 23024650, 2012). "PPARγ has been shown to be highly expressed in tumor endothelium and is activated by rosiglitazone in cultured endothelial cells." (PMID 22934105, 2012). "For example, most studies reported that PPARγ activation inhibited cancer cell proliferation and tumor growth, whereas others found that PPARγ activation potentiates tumorigenesis." (PMID 21664456, 2011). "15-deoxy-delta-12,14-prostaglandin-J2 (15d-PGJ2), an arachidonic metabolite and a natural PPARγ agonist, is known to induce apoptosis in tumor cells." (PMID 21957481, 2011). "The mechanisms by which tumors educate macrophages in the tumor microenvironment and the role of PPARγ in this interaction remain poorly understood." (PMID 22145026, 2011). "In this case, the delay in tumor development was attributed to the upregulation and activation of PPARγ." (PMID 22140470, 2011). "Our in vivo findings of fewer arginase I-positive macrophages tumor-bearing lungs of mice with targeted deletion of PPARγ in myeloid cells are consistent with the in vitro findings and point to a key role for PPARγ in the innate immune system." (PMID 22145026, 2011). "We observed many factors and pathways affected by MT19c, including some related to tumor growth and survival, such as DNA damage response, apopotic genes, insulin, and PPARγ." (PMID 21781307, 2011). "Different types of tissues respond differently to PPARγ activation and the mechanistic data are still missing to explain the mode of its involvement in tumor development." (PMID 21664456, 2011). "We next examined the effect of PPARγ depletion on in vivo tumor growth in both flank and orthotopic xenograft mouse models." (PMID 22194735, 2011). "A novel group of peroxisomal proliferator activated receptor γ (PPARγ) modulating agents sensitize tumor cells to TRAIL-induced apoptosis." (PMID 22091432, 2011). "The importance and meaning of this interaction need to be further analyzed in vivo, given the fact that PPARγ is considered a tumor suppressor gene and clinical trials using PPARγ-agonists in the treatment of cancer are in course." (PMID 24212818, 2011). "As a consequence, PPARγ has been regarded as a possible target for anti-cancer therapy and TZDs have been used in clinical trials for the treatment of tumours involving different organs and tissues, such as prostate, colon, breast, lung and adipose tissue." (PMID 20068562, 2010). "Due to its ability to inhibit angiogenesis, tumor cell invasion, and inflammation, it therefore follows that PPARγ would inhibit metastasis." (PMID 20182546, 2010). "The necessary presence of S100A2 for the maximum antiproliferative effect of PPARs indicates a potential mechanism of tumor response or resistance to PPARγ-directed anticancer therapy." (PMID 20614003, 2010). "Nevertheless, there is evidence in tumor cells that Cav1 and Cav2 are up-regulated by PPARγ in human carcinoma cells; annexin II is up-regulated by PPARγ agonists in 3T3-L1 cells and Cav1 is suppressed by Ras-p42 MAP kinase and PKA." (PMID 20574519, 2010).
tumor (continued). "For example, ligands activating PPARγ were effective in arresting the growth of dedifferentiated tumor cells in multiple tumor types, and they promoted differentiation of tumor cells and inhibited spontaneous metastasis in a xenograft model." (PMID 20214829, 2010). "In conclusion, in this study, we demonstrated that the PPARγ agonist RGZ effectively inhibits tumour growth in a human NB xenograft." (PMID 20068562, 2010). "Based on our experimental data, we proposed that rosiglitazone-induced tumor suppression is due to a combination of PPARγ-dependent and PPARγ-independent pathways." (PMID 20226009, 2010). "In fibrosarcoma cells, the synthetic PPARγ agonist ciglitazone induces tumor cell invasion through the generation of ROS and ERK." (PMID 20182546, 2010). "The PPARγ agonists-induced apoptosis has been described as a surveillance mechanism against tumour growth and invasion in NB." (PMID 20068562, 2010). "Abundant PPARγ expression has been detected in different tumours affecting the nervous system, such as astrocytomas, gliobastomas and NB." (PMID 20068562, 2010). "We had studied such combined tumor-stroma-targeted cancer therapy using PPARG agonists and COX2 inhibitors in the second-line treatment of advanced metastatic melanoma disease." (PMID 19639032, 2009). "In conclusion, combination therapy of a rexinoid with a retinoid or other nuclear hormone receptor, such as PPARγ, has the potential to decrease tumor growth in poorly differentiated cancers with the appropriate protein targets." (PMID 19267912, 2009). "PPARγ inhibition was shown to induce apoptosis and anoikis and inhibit tumor cell invasion in squamous cell carcinomas." (PMID 19794826, 2009). "PPARγ and activators affect tumours by different mechanisms, involving cell proliferation and differentiation, apoptosis, antiinflammatory, and antiangiogenic effects." (PMID 19587804, 2009). "In breast tissue, agonists of PPARγ have been shown to inhibit cell growth, reduce oestrogen production by adipose tissue, inhibit oestrogen receptor (ER) activity and play a role in tumour regression." (PMID 19356226, 2009). "PPARγ expression was detected by inmunohistochemistry in formalin fixed tumors and by western blot in tumor cell lysates." (PMID 18261208, 2008). "To test the anti-tumour activity of PPARγ agonists on BTSCs, we measured cell proliferation in culture." (PMID 19018263, 2008). "Since we first found that murine mammary LMM3 tumor cells expressed PPARγ protein, we performed in vivo experiments to analyze the effect of RGZ, the synthetic compound with high affinity for PPARγ, on primary tumor and lung metastasis development." (PMID 18261208, 2008). "Experimental studiesof human cancer cells and PPARγ have focused primarily on the γ-activating effects of thiazolidinediones, identifying PPARγ agonists as negative regulators of cell growth and tumor progression." (PMID 19125177, 2008). "In vivodata has suggested that PPARγ genetic alteration can lead to cancerdevelopment, while its agonists can inhibit tumor progression." (PMID 19096712, 2008). "GW501516 accelerated the onset of tumor formation during mammarycarcinogenesis, in contrast to the delay of tumor formation by PPARγ agonist GW7845." (PMID 18566686, 2008). "The tumor-bearing Pparγ+/− mice also had a greater number of tumors in them that led tosignificantly decreased survival." (PMID 18784849, 2008). "In this article, we will discuss the opposing effects of TGFβ on tumor growth and metastasis, and address the signaling pathways regulated by PPARγ for tumor progression and suppression." (PMID 18615188, 2008). "Peroxisome proliferator-activated receptor gamma is expressed in many different tissues and regulates lipid metabolism, glucose homoeostasis, tumour progression and inflammation." (PMID 19018263, 2008).
tumor (continued). "Below we summarize the currentknowledge of PPARγ effects and molecular mechanisms and delineateways to augment PPARγ anti-angiogenic and antitumor effectswhile minimizing its pro-angiogenic and tumor-promoting capacities." (PMID 19043603, 2008). "A large study of 126 renal cell carcinomasalso showed significantly more extensive and intensive PPARγ stainingin tumor epithelium compared to the average staining levels seen in 20 normaltissues." (PMID 18784849, 2008). "This is further supported by the finding that PPARγ activatorsexert a potent tumor-suppressing activity against various human cancer cells." (PMID 18615188, 2008). "It acts as adominant-negative receptor of PPARγ, and reduces expression of the Ras tumor suppressor, NORE1A, which inhibits ERKactivation." (PMID 18566686, 2008). "It has also been reported that PPARγ agonists suppress tumor cell invasion in colon and breastcancer cells by downregulation of matrix metalloproteinase-7 (MMP-7) andinduction of MMP inhibitors." (PMID 18551185, 2008). "As Treg activity can impair tumor rejection,PPARγ inhibitors should suppress Treg thereby aiding tumor rejection." (PMID 18509498, 2008). "Mammary gland specific constitutive expression of PPARγ(MMTV-VpPPARγ) didnot yield tumor development." (PMID 18784849, 2008). "Exacerbationof tumor formation by PPARγ wasascribed to increased Wnt-β catenin signaling as demonstrated by zebrafishdevelopmental models." (PMID 18784849, 2008). "This apparent paradoxical synergism between agonists and antagonists is in line with the finding that while PPARγ agonists can possess tumor suppressing effects, antagonists also can induce apoptosis in cancer cells." (PMID 18947424, 2008). "The PPARγ agonists also induced a modest cell cycle arrest and apoptosis in gliosphere cells, suggesting their anti-tumour activity in BTSCs." (PMID 19018263, 2008). "The role ofPPARs, particularly PPARγ, in cancer is an evolving field.Understanding of the molecular mechanisms underlying PPAR-mediated regulationof apoptosis of tumor cells will continue to expand." (PMID 18615184, 2008). "In treated and untreated tumor bearing mice, adipocytes and endothelium showed intense PPARγ staining." (PMID 18261208, 2008). "One protein, thatmay play a role in PPARγ-mediated tumor suppression, is phosphatase andtensin homolog on chromosome ten (PTEN), which has an established role inbreast cancer development." (PMID 19096712, 2008). "In this context, activationof PPARγ has been reported to reduce tumor cellproliferation and invasion and to enhance apoptosis." (PMID 18725983, 2008). "For squamous cell carcinoma, 20 cases ofprimary tumor and six cases of lymph node metastasis were demonstrated to haveincreased PPARγ proteinexpression compared to normal tongue tissue." (PMID 18784849, 2008). "Taken together, data fromboth human and murine cell line studies suggest that PPARγ promotes tumor cell survival under conditionsof nutrient/growth factor deprivation, and that the effect is not limited to aparticular system." (PMID 18784849, 2008). "Similar to colon carcinogenesis, dataon PPARγ'srole in mammary gland carcinogensis suggest a wide range of effect depending onthe tumor models." (PMID 18784849, 2008). "Although short-term interventionwith rosiglitazone did not alter the endpoint of cell proliferation, this pilotstudy indicated the potential for other tumor tissue specific effects withevidence for downregulation of PPARγ protein expression." (PMID 19125177, 2008). "Although there are conflicting reportsof a role for syndecan-1 in cancer, the importance of these studies is theidentification of a PPARγ molecular target that is regulated byPUFAs and results in functional response in the tumor cells." (PMID 18769551, 2008). "Forthe purpose of clarification, we attempted to analyze the published dataaccording to the cancer types, tumor induction models, PPARγ activation/reduction methods, and tumorcharacteristics." (PMID 18784849, 2008).
tumor (continued). "PPARγ agonists have both PPARγ-dependent and -independent effects oncoagulation, thrombosis, angiogenesis, and tumor growth and metastasis." (PMID 18528522, 2008). "Despitethe growing amount of in vitrodata supporting the role of PPARγ as a tumor suppressor, only a small number ofcancers have had their PPARγ status characterized in vivo and there are very few studies ofclinical PPARγ agonist treatment." (PMID 19096712, 2008). "These and other PPARγ agonists have been investigated in vitro in various cancer cell lineswith evidence of growth inhibition and tumor cell apoptosis." (PMID 18989374, 2008). "Several studies indicate that PPARγ inhibitor compounds are also able to reduce tumor growth in preclinical models." (PMID 18509498, 2008). "In salivary duct carcinoma, anaggressive tumor type, PPARγ is highly expressed (80%) and topographically located in the cytoplasm, indicative of an inactivation ofits genomic activities in the nucleus." (PMID 18596912, 2008). "Althoughmost of the antitumor effects of PPARγ ligands are attributed to PPARγ agonists, there is evidence that PPARγ antagonists can have antiproliferative andapoptotic effects on tumor cells." (PMID 18615184, 2008). "We and others have demonstrated PPARγ immunostaining in human breast cancerspecimens, as well as normal and benign proliferative breast tissue." (PMID 19125177, 2008). "Essential to adipocyte differentiation and to regulation of lipid metabolism, PPARγ is thought to have overall tumor suppressive properties, exerted notably in CRC." (PMID 18992148, 2008). "Statistical analysis indeed revealed that expression of PPARγ correlateswith high tumor stage and higher tumor histological grade." (PMID 18784849, 2008). "As PPARγ was shown to be constitutively active in several tumour entities and PPARγ agonists extent strong anticancer effects, the role of PPARγ as a possible target for specific anticancer strategy was investigated in numerous studies." (PMID 18483619, 2008). "Much evidence suggests that PPARγactivity can modulate tumor development, implicating PPARγ as an importanttherapeutic cancer target." (PMID 18509498, 2008). "These systems can be categorized byhow the tumor models are generated and by how the dose/activity of PPARγ is altered." (PMID 18784849, 2008). "Some of the studies, however, identify pro-angiogenic and tumor-promoting effects of PPARγ and its ligands pointing out the need for further studies." (PMID 19043603, 2008). "“In vitro” PPARγ and PPARα were evaluated in human tumor and normal cell lines, treated with natural or synthetic ligands." (PMID 17389773, 2007). "Although differential expression of PPARγ is observed in tumors compared to normal tissues, and PPARγ agonists have been shown to inhibit tumor cell growth and survival, the interdependence of these observations is unclear." (PMID 17584937, 2007). "Treating cells from theseaggressive tumours with ligands for both PPARγ and the retinoid X receptor (RXR) forces their terminal differentiation." (PMID 17710234, 2007). "PPARγ agonists have been demonstrated to show tumour inhibition in vitro and in vivo, in a number of tumour types such as breast and colon." (PMID 16569247, 2006). "Several studies have described increased or decreased levels of PPARγ expression in different human tumour tissue as compared to normal mucosa." (PMID 16854216, 2006). "Previous studies have demonstrated the expression of PPARγ in several tumours including colon, breast, bladder, prostate, lung and stomach." (PMID 15583697, 2005). "The intensity of PPARγ staining was also significantly higher in malignant tumours compared with benign and borderline tumours (χ2=43.93, P<0.001)." (PMID 15583697, 2005). "Out of eight benign and 10 borderline tumours, only one in each group stained positive for PPARγ expression." (PMID 15583697, 2005).